ZNF346 (zinc finger protein 346)
Description:
Binds with low affinity to dsDNA and ssRNA, and with high affinity to dsRNA, with no detectable sequence specificity. May bind to specific miRNA hairpins.
Synonyms: JAZ; Zfp346
Tractability: PROTAC: UniProt records ubiquitination sites on it; ubiquitination databases record sites on it; its protein half-life has been measured.
Gene: Protein-coding gene on chromosome 5 (177,022,696 to 177,081,201, forward strand). Ensembl gene ENSG00000113761.
Subcellular location: Nucleus, nucleolus; Cytoplasm
Subcellular location (Human Protein Atlas): Nucleoplasm
Gene Ontology:
Molecular function: double-stranded RNA binding; enzyme binding; miRNA binding; protein binding; RNA binding; nucleic acid binding; zinc ion binding
Cellular component: nucleolus; nucleoplasm; nucleus; cytoplasm
Genetic constraint (gnomAD): Loss-of-function variants: 22 observed, 25.98 expected, observed/expected ratio (o/e) 0.85, 90% interval 0.6 to 1.21. The upper end of that interval is the gene's LOEUF score, 1.21, which puts it in group 5 of 6, group 1 being the genes least tolerant of losing a copy. Missense variants: 307 observed, 321.74 expected, observed/expected ratio (o/e) 0.95, 90% interval 0.87 to 1.05. Synonymous variants: 125 observed, 124.31 expected, observed/expected ratio (o/e) 1.01, 90% interval 0.87 to 1.17.
Homologues: Orthologues: chimpanzee ZNF346 (99% identical), dog ZNF346 (93% identical), pig ZNF346 (93% identical), rabbit ZNF346 (90% identical), guinea pig ZNF346 (89% identical), mouse Zfp346 (84% identical), rat Zfp346 (82% identical), tropical clawed frog znf346 (47% identical), zebrafish znf346 (43% identical), Drosophila melanogaster dbf (16% identical), Drosophila melanogaster CG1231 (14% identical). Paralogues in human: ZMAT4 (31% identical), ZMAT1 (25% identical), ZNF385B (18% identical), ZNF385C (18% identical), ZNF385D (15% identical), ZNF385A (15% identical), ZMAT3 (13% identical), ZMAT2 (9% identical), KRCC1 (1% identical).
Diseases named in the same sentence as ZNF346 in open-access papers:
ZNF346 is named in the same sentence as 21 diseases in open-access papers, as found by Europe PMC text mining. Sharing a sentence is not in itself a finding about the gene and the disease. The quoted sentences say what the papers report.
colorectal cancer (2 papers, 2015 to 2022). A primary or metastatic malignant neoplasm that affects the colon or rectum. "In this study we assess the zinc finger proteins ZNF346, ZNF638, ZNF700 and ZNF768 as capture antigens for the detection of autoantibodies in colorectal cancer." (PMID 25875936, 2015). "Our results indicate that zinc finger proteins ZNF346, ZNF638, ZNF700 and ZNF768 are suitable for use as capture antigens in a blood-based biomarker assay for colorectal cancer." (PMID 25875936, 2015). "In the current study, we validated the presence of autoantibodies to ZNF346, ZNF638, ZNF700 and ZNF768 in colorectal cancer in an independent and larger patient cohort using the well-established ELISA platform." (PMID 25875936, 2015). "We have previously identified autoantibodies to ZNF346, ZNF638, ZNF700 and ZNF768 in colorectal cancer patients using a 37,830-clone recombinant human protein array." (PMID 25875936, 2015).
neuroblastoma (2 papers, 2018 to 2020). Neuroblastoma (NB) is the most common solid, extracranial childhood tumor. "Here, we found that miR-542-3p was downregulated and KDM1A as well as ZNF346 were upregulated in neuroblastoma tissues and cells." (PMID 33987474, 2020). "Taken together, miR-542-3p mediated the growth of neuroblastoma cells via repressing ZNF346 expression." (PMID 33987474, 2020). "In this study, we confirmed that the overexpression of miR-542-3p suppressed cell proliferation, invasion, and tumor growth via the downregulation of KDM1A and ZNF346 in neuroblastomas." (PMID 33987474, 2020). "The results showed that ZNF346 level was negatively correlated with miR-542-3p level in neuroblastoma tissues." (PMID 33987474, 2020). "Taken together, our data established an association between miR-542-3p and KDM1A/ZNF346, and suggested that miR-542-3p suppressed cell proliferation and invasion via targeting KDM1A and ZNF346 in neuroblastoma." (PMID 33987474, 2020). "Whereas the levels of KDM1A and ZNF346 were increased in neuroblastoma tissues/cells compared to that in normal tissues/cells." (PMID 33987474, 2020). "In recent years, KDM1A and ZNF346 have been reported that they were closely related to neuroblastoma." (PMID 33987474, 2020). "Both KDM1A overexpression and ZNF346 upregulation weakened the effect of miR-542-3p on neuroblastoma cells." (PMID 33987474, 2020). "Our results suggested that miR-542-3p suppressed cell proliferation and invasion by targeting KDM1A and ZNF346 in neuroblastomas, providing a theoretical basis for the treatment of neuroblastoma." (PMID 33987474, 2020). "Therefore, miR-542-3p suppressed cell proliferation and invasion by regulating the levels of KDM1A and ZNF346 in neuroblastoma cells." (PMID 33987474, 2020). "Then, the levels of miR-542-3p, KDM1A, and ZNF346 in neuroblastoma tissues and cells was explored." (PMID 33987474, 2020). "In neuroblastoma, ZNF346 is reported to modulate cell proliferation and apoptosis." (PMID 33987474, 2020). "Similarly, present evidence demonstrated that ZNF346 acted as an oncogene for the development of neuroblastoma." (PMID 33987474, 2020). "Firstly, the levels of miR-542-3p, KDM1A and ZNF346 were determined in neuroblastoma." (PMID 33987474, 2020). "Furthermore, a new mechanism that miR-542-3p affecting neuroblastoma cell growth through modulating KDM1A and ZNF346 levels was confirmed." (PMID 33987474, 2020). "Based on these results, we speculated that miR-542-3p inhibited neuroblastoma cell development through the downregulation of KDM1A and ZNF346." (PMID 33987474, 2020).
chronic hepatitis (1 paper, 2023). An active inflammatory process affecting the liver for more than six months. "We downloaded the gene expression profiles of 94 samples covering different stages of HCC from GSE89377, found that the expression of ZNF385A and ZNF346 gradually increased from chronic hepatitis to liver cirrhosis and HCC." (PMID 36834567, 2023). "Finally, a dataset covering the different stages of hepatocellular carcinoma showed a trend of progressive increase in ZNF385A and ZNF346 expression, from chronic hepatitis to hepatocellular carcinoma." (PMID 36834567, 2023).
colon cancer (1 paper, 2022). "However, in the current state of the research, there are still many ZFPs whose mechanisms of action in colon cancer are not fully understood, and more mechanisms need to be further studied, such as ZNF146, ZNF511, ZNF346, ZNF638, ZNF700, and ZNF768." (PMID 36358661, 2022).
liver cancer (1 paper, 2023). An epithelial or non-epithelial malignant neoplasm that arises from the liver. "By performing TIDE analyses and survival analyses in one liver cancer and one urothelial cancer cohort receiving anti-PD-1/anti-PD-L1 therapy, we observed that ZNF385A and ZNF346 performed well in predicting the responses to ICI therapy." (PMID 36834567, 2023). "In conclusion, ZNF385A and ZNF346 are promising candidate biomarkers for the diagnosis, prognosis, and response to immunotherapy in HCC, and this study may help to understand the tumor microenvironment (TME) of liver cancer, and to develop new therapeutic targets." (PMID 36834567, 2023).
renal carcinoma (1 paper, 2015). A carcinoma arising from the epithelium of the renal parenchyma or the renal pelvis. "A more recent study further confirmed our discovery of ZNF346 autoantibodies when sera of renal cancer patients were analysed." (PMID 25875936, 2015).
cancer (4 papers, 2015 to 2023). A tumor composed of atypical neoplastic, often pleomorphic cells that invade other tissues. "As the VEGF signaling pathway was enriched in the ZNF385A- and ZNF346-high groups, we predicted the chemotherapeutic response of sorafenib for each sample, based on the Genomics of Drug Sensitivity in the Cancer (GDSC) database." (PMID 36834567, 2023). "ZNF385A and ZNF346 both belong to RNA binding proteins, and they have very similar structures; however, there are very few studies in cancers." (PMID 36834567, 2023). "ZNF385A and ZNF346 were also ubiquitously expressed in a variety of cancer cell lines, based on the screening of expression data from the Cancer Cell Lineage Encyclopedia (CCLE) dataset." (PMID 36834567, 2023). "This provoked us to explore whether ZNF385A and ZNF346 are involved in cancer initiation and progression." (PMID 36834567, 2023). "We first investigated the pan-cancer expression patterns of ZNF385A and ZNF346 via the Cancer Genome Atlas (TCGA) and Genotype Tissue Expression (GTEx) datasets." (PMID 36834567, 2023). "Autoantibodies to ZNF346 were detected in the sera of 15 out of 96 CRC patients (15.6%) and in 2 out of 35 non-cancer control samples (5.7%)." (PMID 25875936, 2015).
tumor (3 papers, 2020 to 2023). "We used the Tumor Immune Dysfunction and Exclusion (TIDE) score to assess the efficacy of immunotherapy in different ZNF385A and ZNF346 subgroups." (PMID 36834567, 2023). "From these data, it was possible that miR-542-3p acted as a tumor suppressor, and KDM1A as well as ZNF346 exerted oncogenic function." (PMID 33987474, 2020). "According to the Tumor Immune Estimation Resource (TIMER) database, ZNF385A and ZNF346 were significantly positively correlated with six main infiltrating immune cells in HCC, such as B cells, CD8 T cells, CD4 T cells, macrophages, dendritic cells, and neutrophils." (PMID 36834567, 2023).
neurodegenerative disease (1 paper, 2018). A disorder of the central nervous system characterized by gradual and progressive loss of neural tissue and neurologic function. "ZNF346 is a member of the C2H2-type zinc finger proteins that has a neuroprotective role in neurodegenerative disease models." (PMID 29793538, 2018).
ZNF346 also shares sentences with these, for which no sentence is quoted: infection (8 papers); bacterial diseases (1); hepatocellular carcinoma (1); liver cirrhosis (1); melanoma (1); metastatic cancers (1); metastatic tumor (1); nutritional deficiency (1); Pan (1); potassium (1); thymoma (1); uveal melanoma (1).